RIPK3 (receptor interacting serine/threonine kinase 3)
Diseases named in the same sentence as RIPK3 in open-access papers (continued):
Sharing a sentence is not in itself a finding about the gene and the disease.
pulmonary fibrosis (7 papers, 2021 to 2026). Chronic progressive interstitial lung disorder characterized by the replacement of the lung tissue by connective tissue, leading to progressive dyspnea, respiratory failure, or right heart failure. "By constructing RIPK3 adenovirus vector, some studies further confirmed that the increase of RIPK3 expression induced by JNK activation was the cause of pulmonary fibrosis in mice." (PMID 36841823, 2023). "The translational potential of this finding was validated, as lung-specific Ripk3 knockdown also attenuated lung fibrosis." (PMID 41709822, 2026). "Here, we identify a distinct, necroptosis-independent immunometabolic function of RIPK3 in regulating pulmonary fibrosis." (PMID 41709822, 2026). "JNK inhibition ameliorated pulmonary fibrosis in Sftpa1-KI mice, but it was blocked with RIPK3 overexpression." (PMID 34594225, 2021). "Mutation in SFTPA1 resulted in IPF in a consanguineous Japanese family, and SFTPA1 knock-in (Sftpa1-KI) mice spontaneously developed pulmonary fibrosis with increased necroptosis derived by c-Jun N-terminal kinase (JNK)-mediated upregulation of RIPK3 in AEC2s." (PMID 34594225, 2021). "Initiation of the Ripk3 signaling pathway promotes fibroblast activation and proliferation in lung tissue, increases extracellular matrix deposition and influences extracellular matrix remodeling, providing a cellular basis for the development of pulmonary fibrosis." (PMID 39744171, 2025). "Genetic or pharmacological inhibition of RIPK3 reduces HMGB1 release in pulmonary fibrosis and subarachnoid hemorrhage models, and reduced HMGB1 signaling could indirectly contribute to improved functional outcome in CCI because of its role in IL-1 beta production via toll-like receptor signaling." (PMID 34753914, 2021). "However, due to the strict setting of our logFC cutoff value, Therefore, RIPK3 and MLKL were not included into the DEGs in the previous analysis of pulmonary fibrosis tissue in GSE110147, so we conducted a follow-up animal experiment for additional verification." (PMID 37051233, 2023).
Splenomegaly (7 papers, 2019 to 2024). Abnormal increased size of the spleen. "At age of 16 weeks, similar as RIPK3 and Caspase8 deficient mice, the Ripk1Y383F/Y383FRipk3−/−Caspase-8−/− mice also showed dramatic splenomegaly which is caused by massive infiltration of CD3+B220+ lymphocytes." (PMID 36329033, 2022). "Ripk1K612R/K612R mice are viable, but develop age-dependent reduction of RIPK1 expression, spontaneous intestinal inflammation and splenomegaly, which can be rescued by antibiotic treatment and partially by Ripk3 deficiency." (PMID 33311474, 2020). "Necroptosis‐independent RIPK3 function contributes to anemia, while co‐deletion of Ifnar1 rescues anemia, thrombocytopenia, and splenomegaly, highlighting ABIN1 (Q478) as a regulator of hematopoietic deficiencies through type I IFN expression." (PMID 38009796, 2024). "Although Abin1Q478H/Q478H cells are sensitive to RIPK1 kinase–RIPK3–MLKL‐dependent necroptosis, only anemia and splenomegaly are alleviated by RIPK3 deficiency but not by MLKL deficiency or the RIPK1 kinase‐dead mutation." (PMID 38009796, 2024). "Ripk3 deficiency could alleviate anemia and splenomegaly—but not thrombocytopenia—in a necroptosis‐independent manner in Abin1Q478H/Q478H mice." (PMID 38009796, 2024). "By crossing RIPK3‐knockout mice with Abin1Q478H/Q478H mice, we generated Abin1Q478H/Q478HRipk3–/– mice, which displayed increased RBC and hemoglobin levels as well as alleviated splenomegaly compared with Abin1Q478H/Q478H mice." (PMID 38009796, 2024).
acute respiratory distress syndrome (6 papers, 2016 to 2023). Progressive and life-threatening pulmonary distress in the absence of an underlying pulmonary condition, usually following major trauma or surgery. "As the co-chaperone of HSP90, PTGES3 (P23) has been found can activate the RIPK3/MLKL during the necroptosis in acute respiratory distress syndrome." (PMID 38020922, 2023). "Deletion of Nec-1 or RIPK3 genes inhibits necroptosis and improves the lung status of animals with acute respiratory distress syndrome." (PMID 36110858, 2022). "Interestingly, it was recently shown that lung injury observed upon high-dose-LPS-induced acute respiratory distress syndrome in mice was due to RIPK3-mediated necroptosis." (PMID 29042502, 2017). "Necroptosis, a form of programmed cell death mediated by receptor interacting serine/threonine-protein kinase-3 (RIPK3), is implicated in murine models of acute respiratory distress syndrome (ARDS)." (PMID 31253195, 2019). "The concentration of phosphorylated RIPK3 and MLKL increased as the LPS dosage increased in an acute respiratory distress syndrome animal model." (PMID 36110858, 2022).
Gaucher disease (6 papers, 2019 to 2026). Gaucher disease (GD) is a lysosomal storage disorder encompassing three main forms (types 1, 2 and 3), a fetal form and a variant with cardiac involvement (Gaucher disease - ophthalmoplegia - cardiovascular calcification or Gaucher-like disease). "It is also known that RIPK1 and RIPK3 expression levels are increased in the brains of mice with Gaucher disease and Niemann-Pick disease." (PMID 36778591, 2022). "When c-Abl is inhibited, a decrease in RIPK3 signaling has been observed in models of Gaucher disease." (PMID 36778591, 2022). "Among the lysosomal storage diseases, RIPK3 was shown to have a role in the pathogenesis of Gaucher’s disease and Niemann–Pick disease." (PMID 33513913, 2021). "When Gaucher disease was induced chemically in a mouse strain in which Ripk3 is ablated, the course of the neurological disease was attenuated with better motor function and greater survival." (PMID 34172992, 2021). "Gaucher’s disease is associated with a strong hyperinflammation and splenomegaly and interestingly, in mouse models, it was shown that it could be largely blocked by loss of RIPK3, suggesting a potential role for RIPK3 mediated cell death as a possible driver of the disease." (PMID 31131275, 2019). "Furthermore, abolition of Ripk3 in a model of neuronopathic Gaucher disease improved the condition." (PMID 34172992, 2021). "While it has not directly been shown that Niemann Pick is regulated by RIPK3 in a similar fashion to Gaucher’s disease, the possibility remains." (PMID 31131275, 2019).
Myocardial fibrosis (6 papers, 2022 to 2023). "The test results showed that depletion of RIPK3 significantly improved the degree of collagen deposition and myocardial fibrosis." (PMID 37833985, 2023). "As expected, cardiac dysfunction, ventricular dilation, and myocardial fibrosis were detected in Tab2fl/fl-MerCreMer Ripk3+/+ mice after tamoxifen treatment." (PMID 34990405, 2022). "The results showed that depletion of RIPK3 significantly improved the degree of collagen deposition and myocardial fibrosis." (PMID 35571197, 2022). "We hypothesized that RIPK1/RIPK3 activation mediated myocardial fibrosis by impairing the autophagic flux." (PMID 35165268, 2022). "Therefore, the researchers hypothesized that NRF2 activation downregulated Ripk3 and ameliorated mitochondrial disease, thus improving myocardial fibrosis." (PMID 35721561, 2022). "In conclusion, HGF induces myocardial fibrosis and cardiac dysfunction by activating the RIPK1-RIPK3 pathway and by impairing the autophagic flux, which is obviated by the pharmacological and genetic inhibition of RIPK1/RIPK3." (PMID 35165268, 2022). "We found that HGF induced myocardial fibrosis and cardiac dysfunction, which corresponded to RIPK1/RIPK3 activation and up-regulation of autophagic related proteins in both in vitro and in vivo models." (PMID 35165268, 2022).
non-small cell lung carcinoma (6 papers, 2020 to 2025). A group of at least three distinct histological types of lung cancer, including non-small cell squamous cell carcinoma, adenocarcinoma, and large cell carcinoma. "Genetic data suggested that necroptosis was the predominant RCD mechanism in non-small cell lung cancer (NSCLC) cells expressing high RIPK3 levels after ablative hypo-fractionated RT." (PMID 36532071, 2022). "In non-small cell lung cancer (NSCLC), reduced expression of RIPK3 and MLKL is significantly associated with poor patient prognosis, suggesting that pathway inactivation may promote tumor immune evasion." (PMID 41267084, 2025). "In non-small cell lung carcinoma (NSCLC), cells characterized by low RIPK3 expression exhibit a dual activation of both apoptosis and necroptosis, with the mode being dose-dependent." (PMID 38323315, 2024). "The successful induction of necroptosis with IR in non-small cell lung cancer (NSCLC) cells depends on irradiation dose, fractionation schedule, and RIPK3 expression." (PMID 34489957, 2021). "Here, we investigated the prognostic value of RIPK3 and CHIP expression in 404 patients with non-small cell lung cancer (NSCLC)." (PMID 32521727, 2020).
pancreatitis (6 papers, 2015 to 2023). Inflammation of the pancreas. "The authors showed a significant reduction in the number of dead pancreatic cells, again implying that the kinase function of RIPK3 was critical in mediating acinar cell loss in this pancreatitis model." (PMID 37409125, 2023). "However, in another caerulein-induced-pancreatitis study using RIPK3- or MLKL-deficient mice, compared with the control group, the pancreatic edema and inflammation in RIPK3−/− and MLKL−/− mice were more severe, and more inflammatory cells were recruited into the pancreas." (PMID 35740953, 2022). "Although blocking RIPK3 seems to lower pancreatitis severity, the contribution of necroptosis-independent functions of RIPK3 needs to be investigated." (PMID 37409125, 2023). "The authors showed that in mice bearing a mutation in the RIPK1 kinase domain a germline deficiency of the RIPK1 kinase domain or of RIPK3 were not rescued from cerulein-induced pancreatitis." (PMID 37409125, 2023). "In the present study, experimental pancreatitis was induced in C57BL/6J, Ripk3-/- and Mlkl-/- mice by cerulein plus lipopolysaccharide in vivo, and primary pancreatic acinar cells were also isolated to uncover cellular mechanisms during cerulein stimulation in vitro." (PMID 36828808, 2023).
abdominal aortic aneurysm (5 papers, 2020 to 2024). Enlargement and ballooning of the vessel that supplies arterial blood to the abdomen, pelvis and legs. "We have previously demonstrated that RIPK3-mediated SMC necroptosis contributes to abdominal aortic aneurysm pathophysiology." (PMID 34572045, 2021). "Receptor interacting protein kinase 3 (RIPK3)-mediated smooth muscle cell (SMC) necroptosis has been shown to contribute to the pathogenesis of abdominal aortic aneurysms (AAAs)." (PMID 34572045, 2021). "Wang and his colleagues observed that the expressions of RIPK1 and RIPK3 were elevated in human abdominal aortic aneurysm, especially medial smooth muscle cells, and the level of RIPK3 was also elevated in the mouse model of abdominal aortic aneurysm." (PMID 34977874, 2021). "Finally, in the elastase-induced abdominal aortic aneurysm model, mice with RIPK3−/− or RIPK3+/− exhibited more resistance to aneurysm growth and TNF-mediated inflammatory responses in cardiac smooth muscle cells." (PMID 36361505, 2022).
cardiomyopathy (5 papers, 2018 to 2025). A disease of the heart muscle or myocardium proper. "We found that DMF exhibited beneficial effects in PM2.5-induced cardiomyopathy by inhibiting RIPK3 expression, oxidative stress, fibrosis and inflammation via the up-regulation of Nrf2." (PMID 32182211, 2020). "The in vivo results above indicated that promoting Nrf2 expression could alleviate PM2.5-induced cardiomyopathy by preventing RIPK3 expression, oxidative stress, fibrosis and inflammation." (PMID 32182211, 2020). "Along with the well-documented role of RIPK3-mediated mitophagy in tissue injury, we asked if RIPK3-regulated mitochondrial function could be regulated by Nrf2 in the setting of PM2.5-induced cardiomyopathy." (PMID 32182211, 2020). "As far as we know, it was the first study that Nrf2 exhibited a significant protective role against PM2.5-induced cardiomyopathy through suppressing collagen accumulation, oxidative stress and inflammation regulated by RIPK3, as well as the improvement of autophagy and glucose metabolism in hearts." (PMID 32182211, 2020). "Furthermore, RIPK3 depletion ameliorates cardiomyopathy in mdx mice, suggesting that necroptosis inhibition may have multiorgan benefits in DMD, tackling cell degeneration together with locomotor, respiratory and heart muscles." (PMID 36613804, 2022). "RIPK1 and RIPK3 are upregulated in DMD rats, which develop a significant cardiomyopathy." (PMID 36613804, 2022).
diabetic nephropathy (5 papers, 2020 to 2025). "It was speculated that high glucose-induced necroptosis mediated by TNF might be further regulated by ubiquitin carboxy-terminal hydrolase L1 (UCHL1) via the RIPK1/RIPK3 pathway, leading to enhanced progression of diabetic nephropathy and increased podocyte injury and loss." (PMID 36756299, 2023). "In human kidney biopsies from CKD patients with diabetic nephropathy and histological evidence of tubulointerstitial fibrosis, RIPK3 expression is increased compared with control kidney tissue." (PMID 39544363, 2024). "In summary, the results from these animal studies have demonstrated that RIPK3 is an important mediator of tubulointerstitial fibrosis in diabetic kidney disease." (PMID 32591618, 2020). "This study was undertaken to define the role of RIPK3 in regulating tubulointerstitial fibrosis in diabetic nephropathy." (PMID 32591618, 2020). "Our data indicate that RIPK3 activity is upregulated within the kidney in the context of diabetic kidney disease." (PMID 32591618, 2020). "Receptor‐interacting protein kinase 3 (RIPK3) is a key player in necroptosis and an emerging inflammation regulator, whose contribution to podocyte injury in diabetic kidney disease (DKD) remain unclear." (PMID 40539374, 2025). "Thus, curcumin might be a potential therapeutic agent for diabetic nephropathy as an inhibitor of RIPK3." (PMID 35706905, 2022). "Thus, RIPK3 may be a potential target for therapeutic intervention in patients with diabetic kidney disease." (PMID 32591618, 2020). "Hence strategies that include inhibition of RIPK3 may limit the development of diabetic kidney disease." (PMID 32591618, 2020). "Ripk3 knockout also reduces kidney fibrosis in mouse models of adenine-induced CKD, UUO and diabetic nephropathy." (PMID 39544363, 2024). "RIPK3 activity and NLRP3 expression were upregulated and fibrotic responses were increased in the kidney cortex of WT mice with established diabetic nephropathy compared to control mice." (PMID 32591618, 2020). "Phosphorylation of RIPK3 (p-RIPK3) was examined using western blot in kidneys of WT mice with or without diabetic nephropathy." (PMID 32591618, 2020).
encephalitis (5 papers, 2020 to 2023). An acute inflammatory process affecting the brain parenchyma. "It is possible that a failure to induce ZBP1-RIPK3–mediated cell death underlies the encephalitis phenotype, although RIPK3 may also function downstream of TNF receptor 1 or TLR3 to induce neuronal death and restrict viral replication." (PMID 37450010, 2023). "Here, we use a model of Langat virus (LGTV) encephalitis to show that RIPK3 signaling is specifically required in neurons of the cerebellum to control LGTV replication and restrict disease pathogenesis." (PMID 38011306, 2023). "The same year, RIPK3 was found to restrict WNV pathogenesis independently of cell death in a mouse model of WNV encephalitis." (PMID 34322024, 2021). "RIPK3 restricts WNV pathogenesis by inhibiting necroptosis in a mouse WNV encephalitis." (PMID 34322024, 2021). "We believe that RIPK3 may be a new therapeutic target for the development of virus replication inhibitors to treat JEV-induced encephalitis." (PMID 32265853, 2020).
Hyperglycemia (5 papers, 2022 to 2025). An increased concentration of glucose in the blood. "Thus, the RIPK1/RIPK3 pathway is a promising target for alleviating MF induced by hyperglycemia." (PMID 35165268, 2022). "This work also revealed that CRISPR-mediated gene editing of Ripk3 protects NIT-1 β-cells from TNFα-induced cell death independent of caspase 3/7 activation in vitro, and that RIPK3 knockout mice are protected from STZ-induced hyperglycemia in vivo." (PMID 38842911, 2024).
liver cancer (5 papers, 2021 to 2024). An epithelial or non-epithelial malignant neoplasm that arises from the liver. "Because MASH is a risk factor for liver cancer, we evaluated the impact of overexpressing Ripk3 or Mlkl on liver cancer." (PMID 39514172, 2024). "Liver cancer cells are also shown to prevent MLKL-mediated necroptosis by epigenetic silencing of Ripk3." (PMID 38474061, 2024). "We directly assessed the role of necroptosis in the liver on CLD and liver cancer using two knockin mouse models in which two genes involved in necroptosis (Ripk3 and Mlkl) were overexpressed specifically in liver (hepatocytes): hRipk3-KI and hMlkl-KI mice." (PMID 39514172, 2024). "Up-regulation of RIPK3 can prevent the development of liver cancer." (PMID 36353119, 2022). "Because Ripk3 and Mlkl are involved in pathways other than necroptosis, it was important for us to show that similar changes in CLD and liver cancer occurred in both hRipk3-KI and hMlkl-KI mice to demonstrate conclusively that necroptosis was responsible for the changes that we observed." (PMID 39514172, 2024). "It looks like RIPK1 has a short survival when highly expressed and the expression of RIPK3 has no obvious effect on the survival of liver cancer." (PMID 33440739, 2021).
rheumatoid arthritis (5 papers, 2017 to 2025). A chronic, systemic autoimmune disorder characterized by inflammation in the synovial membranes and articular surfaces. "In addition to rheumatoid arthritis, we have found that RIPK3 contributes to osteoarthritis (OA), through roles at least partly independent of MLKL activation." (PMID 36224345, 2022). "Our findings reveal that RIPK3 plays an active role in the progression of rheumatoid arthritis rather than being a mere bystander or consequence of inflammation." (PMID 40963902, 2025).
systemic lupus erythematosus (5 papers, 2016 to 2023). An autoimmune multi-organ disease typically associated with vasculopathy and autoantibody production. "We therefore carried out studies to investigate the role of RIPK3-mediated necrotic cell death in the humoral immune response during lupus, as well as to identify its role in direct kidney damage during lupus nephritis." (PMID 27669412, 2016). "We conclude that RIPK3 is dispensable for the pathogenesis of lupus and immune mediated nephropathy as to accelerate, worsen or ameliorate the disease." (PMID 27669412, 2016). "Activation of necroptosis by RIPK3 or MLKL in macrophages is dependent on DNA sensing and is elevated in autoimmune conditions like systemic lupus erythematosus (SLE)." (PMID 38139802, 2023). "A second pathway mediating necrosis involves Receptor-Interacting Serine-Threonine Kinase 3 (RIPK3); in this study we sought to investigate the impact of RIPK3 on the development of lupus and nephritis in both sexes." (PMID 27669412, 2016). "We found that the absence of RIPK3 has neither positive nor negative impact on the disease development or progression of lupus and nephritis in all three models, and in both male and female mice." (PMID 27669412, 2016). "We demonstrated that RIPK3 does not affect the production of autoantibodies occurring during the murine lupus model cGvHD." (PMID 27669412, 2016).